MYL6 (myosin light chain 6)
Description:
Regulatory light chain of myosin. Does not bind calcium.
Synonyms: LC17; MLC-3; ESMLC; MLC3NM; MLC1SM; LC17-GI; LC17-NM; LC17A; LC17B; MLC3SM
Tractability: PROTAC: ubiquitination databases record sites on it; its protein half-life has been measured.
Gene: Protein-coding gene on chromosome 12 (56,158,345 to 56,163,496, forward strand). Ensembl gene ENSG00000092841.
Pathways (Reactome):
Signal Transduction: RHO GTPases Activate ROCKs; RHO GTPases activate CIT; RHO GTPases activate PAKs; RHO GTPases activate PKNs
Developmental Biology: EPHA-mediated growth cone collapse; Sema4D induced cell migration and growth-cone collapse
Muscle contraction: Smooth Muscle Contraction
Gene Ontology:
Molecular function: protein binding; structural constituent of muscle; cytoskeletal motor activity; microfilament motor activity; calcium ion binding
Biological process: muscle contraction; muscle filament sliding; skeletal muscle tissue development
Cellular component: brush border; extracellular exosome; membrane; vesicle; cytosol; myosin complex; myosin II complex; unconventional myosin complex
Genetic constraint (gnomAD): Loss-of-function variants: 20 observed, 21.53 expected, observed/expected ratio (o/e) 0.93, 90% interval 0.65 to 1.35. The upper end of that interval is the gene's LOEUF score, 1.35, which puts it in group 5 of 6, group 1 being the genes least tolerant of losing a copy. Missense variants: 164 observed, 201.04 expected, observed/expected ratio (o/e) 0.82, 90% interval 0.72 to 0.93. Synonymous variants: 77 observed, 75.24 expected, observed/expected ratio (o/e) 1.02, 90% interval 0.85 to 1.24.
Homologues: Orthologues: macaque MYL6 (99% identical), pig MYL6 (94% identical), rat Myl6 (94% identical), zebrafish myl6 (78% identical), tropical clawed frog myl6 (72% identical), zebrafish zgc:153867 (66% identical), Drosophila melanogaster Mlc-c (50% identical), Caenorhabditis elegans mlc-5 (44% identical), Caenorhabditis elegans mlc-6 (41% identical). Paralogues in human: MYL6B (80% identical), MYL4 (77% identical), MYL1 (73% identical), MYL3 (73% identical).
Diseases named in the same sentence as MYL6 in open-access papers:
MYL6 is named in the same sentence as 30 diseases in open-access papers, as found by Europe PMC text mining. Sharing a sentence is not in itself a finding about the gene and the disease. The quoted sentences say what the papers report.
Obesity (5 papers, 2020 to 2024). Accumulation of substantial excess body fat. "Furthermore, MYL6 exhibited elevated expression in conditions such as obesity, asthma, and cervical cancer, yet the underlying mechanisms remain not fully elucidated." (PMID 38812509, 2024). "MYL6 is an ATPase cellular motor protein that is highly expressed in obesity, asthma, and cervical cancer, but the potential mechanisms are not fully known." (PMID 33343487, 2020). "Moreover, higher differences in MYL6 gene expression were found in placenta of pregnant women with obesity compared to lean matching controls." (PMID 38703299, 2024). "They identified 34 shared loci among 3 obesity-related traits and 2 asthma subtypes and, utilizing an obesity mouse model, identified 2 genes (acyl-coenzyme A oxidase-like (ACOXL) and myosin light chain 6 (MYL6)) playing a significant role in both diseases." (PMID 36013497, 2022).
melanoma (3 papers, 2019 to 2024). A malignant, usually aggressive tumor composed of atypical, neoplastic melanocytes. "A gene expression array confirmed a positive correlation between ADCK2 expression and RAB2A (Ras-related protein Rab-2A) and MYL6 expression in different melanoma cell lines." (PMID 35205819, 2022). "Since knocking down ADCK2 significantly altered the migration capacity of melanoma cells, we also performed a wound healing migration assay after knocking down MYL6 in OE ADCK2 cells." (PMID 35205819, 2022). "The fact that a lower intratumoral expression of ADCK2, as well as MYL6, in melanoma is connected with a poor prognosis for melanoma patients allows the conclusion that ADCK2 might be a tumor suppressor in melanoma." (PMID 35205819, 2022). "In this study, we could demonstrate that ADCK2 affects different properties of melanoma cells and that these effects are mediated via MYL6." (PMID 35205819, 2022). "Interestingly, it predicted positive association in breast cancer through co-relation with MYL6, RABAC1 and other genes, while negatively regulating ATL2, ICE2 and TADA1 in melanoma and HCC." (PMID 30857225, 2019). "ADCK2 could control the migration of melanoma cells by affecting the formation of NM2s via MYL6." (PMID 35205819, 2022). "To further investigate if the effect of ADCK2 on viability and migration was mediated via MYL6, we ectopically overexpressed ADCK2 while simultaneously knocking down MYL6 in melanoma cell lines." (PMID 35205819, 2022).
microscopic polyangiitis (2 papers, 2022 to 2024). Microscopic polyangiitis (MPA) is an inflammatory, necrotizing, systemic vasculitis that affects predominantly small vessels (i.e. small arteries, arterioles, capillaries, venules) in multiple organs. "The study has revealed that anti-MYL6 antibody can decrease the disease activity of microscopic polyangiitis by damaged actin rearrangement necessary for neutrophil extracellular trap formation." (PMID 39262873, 2024).
acute myocardial infarction (1 paper, 2025). Necrosis of the myocardium, as a result of interruption of the blood supply to the area. "Elevated expression levels of RAC1, IQGAP1, MYL6, DBN1, SLC2A1 and SLC2A3 were observed in acute myocardial infarction patients compared to healthy controls, suggesting a strong association with disease progression and indicating their potential as novel therapeutic targets." (PMID 40672380, 2025).
aneurysm (1 paper, 2024). Bulging or ballooning in an area of an artery secondary to arterial wall weakening. "Comparing smooth muscle cell markers such as Acta2, Tagln, Myl9, Myl6, Cnn1, and Myh11, these markers were expressed less in thoracic aneurysm SMCs, suggesting a less-differentiated state of the thoracic aneurysm SMCs." (PMID 39590192, 2024).
bladder cancer (1 paper, 2024). "Most disulfidoptosis genes were downregulated in multiple cancer types, including PDLIM1, TLN1, and MYH10 in lung squamous cell carcinoma (LUSC), MYL6 and DSTN in prostate adenocarcinoma (PRAD), and FLNA and ACTB in bladder cancer (BLCA)." (PMID 38862242, 2024).
bladder urothelial carcinoma (1 paper, 2024). "Single-cell analysis revealed that ACTB, DSTN, and MYL6 were highly expressed in different bladder urothelial carcinoma subtypes, but MYH10 showed a low expression." (PMID 38584831, 2024).
chronic kidney disease (1 paper, 2024). Impairment of the renal function secondary to chronic kidney damage persisting for three or more months. "The proteomic analysis of an advanced chronic kidney disease (CKD) cohort identified that proteins SPTA1, MYL6 and C6, when used alongside the 4-variable UK-KFRE, achieve an improved performance when predicting a 5-year risk of ESRD." (PMID 38762513, 2024).
deep vein thrombosis (1 paper, 2021). "Myosin light polypeptide 6 (MYL6) expression decreased in the platelets of patients with deep vein thrombosis (DVT)." (PMID 33996895, 2021).
lung carcinoma (1 paper, 2022). "In lung carcinoma, a machine learning model could associate MYL6 expression with an “alive without cancer” group, and in a neuroblastoma patient cohort, a higher intratumoral expression of MYL6 promised a better outcome." (PMID 35205819, 2022).
multiple sclerosis (1 paper, 2024). A progressive autoimmune disorder affecting the central nervous system resulting in demyelination. "Previous studies have identified a close association between MYL6 and the inflammatory disease Multiple Sclerosis, suggesting its predictive value for prognosis." (PMID 38812509, 2024).
non-alcoholic fatty liver (1 paper, 2024). A benign form of fatty non-alcoholic fatty liver disease where the disease has not yet progressed to the inflammation of liver. "Previous studies have identified MYL6 as a disulfidptosis-related gene through bioinformatics, which may be involved in the occurrence and development of diseases such as Alzheimer’s and non-alcoholic fatty liver." (PMID 39262873, 2024).
Sepsis (1 paper, 2024). Sepsis is defined as life-threatening organ dysfunction caused by a dysregulated host response to infection. "With an OR of 2.169 (95% CI = 1.259–3.736, p = 0.005), we discovered a strong association between the MYL6 gene and the risk of sepsis (a 28-day death in critical care) using the IVW technique." (PMID 39262873, 2024). "In the present study, we used ROC curve analysis to evaluate the potential diagnostic value of ACSL4 and MYL6 in sepsis." (PMID 39262873, 2024). "With MR analysis, we also carried further and discovered a causal relationship between MYL6 and sepsis (a 28-day death in critical care)." (PMID 39262873, 2024). "In this study, the SNP (rs35436573) in the MYL6 gene was found to be associated with the survival rate of sepsis by MR-related analysis, suggesting that genetic variation in the gene may influence individual responses to sepsis." (PMID 39262873, 2024). "We have discovered and confirmed that the key genes ACSL4 and MYL6, which are linked to disulfidptosis in sepsis-induced acute lung injury, may be useful in the diagnosis and management of septic acute lung injury." (PMID 39262873, 2024). "In addition, a series of bioinformatics analyses and related experimental studies in this study suggested that MYL6 was associated with ALI in sepsis." (PMID 39262873, 2024). "Then, we analyzed MYL6 co-expression genes associated with sepsis in the same way." (PMID 39262873, 2024). "Finally, we explored the causal relationship between MYL6 and sepsis." (PMID 39262873, 2024). "Finally, MR analysis revealed a causal relationship between MYL6 and sepsis." (PMID 39262873, 2024). "Previous studies suggested that ACSL4 and MYL6 co-expression genes were closely associated with inflammatory response, immunosuppression, cell function metabolism, and other aspects in the progression of sepsis, which was consistent with our conjecture and research." (PMID 39262873, 2024). "ACSL4 and MYL6 mRNA expressions were significantly upregulated in sepsis groups compared with control groups (p < 0.001)." (PMID 39262873, 2024). "To further investigate the potential relationship and the underlying mechanisms between key genes and sepsis, we acquired ACSL4 and MYL6 co-expression genes from the Coexpedia dataset and then intersected with 403 DEGs in sepsis." (PMID 39262873, 2024). "After identifying ACSL4 and MYL6 as the key genes between DEGs in sepsis and DRGs, we further explored the mRNA levels of two key genes in the GSE26378, GSE28750, and GSE65682 datasets separately." (PMID 39262873, 2024). "The expressions of ACSL4 and MYL6 mRNA in the GSE95233 dataset were significantly increased in the sepsis group compared with the control group (p < 0.001)." (PMID 39262873, 2024). "This article identifies for the first time MYL6 as a disulfidptosis-related gene involved in sepsis-induced acute lung injury." (PMID 39262873, 2024). "Consistent with earlier results from our study, it is clear that MYL6 overexpression plays a major role in the pathophysiology of sepsis." (PMID 39262873, 2024). "Additionally, both in vivo and in vitro experiments confirmed that the mRNA levels of ACSL4 and MYL6 in sepsis-induced acute lung injury were consistent with the results of bioinformatics analysis." (PMID 39262873, 2024). "If changes in the expression of the MYL6 gene result in a more severe inflammatory response or lung injury, then they may reduce survival in sepsis." (PMID 39262873, 2024). "In the study, the causal link between sepsis and ACSL4/MYL6 was further investigated." (PMID 39262873, 2024). "Finally, to investigate the relationship between genetic variants of MYL6 or ACSL4 and sepsis, Mendelian randomization (MR) analysis was applied." (PMID 39262873, 2024). "The results indicated that both two key genes ACLS4 and MYL6 might contribute to the immune infiltration status of patients with sepsis." (PMID 39262873, 2024).
Sepsis (continued). "Additionally, how ACSL4 and MYL6 regulate the involvement of disulfidptosis in the occurrence of acute lung injury in sepsis is also our next research direction." (PMID 39262873, 2024). "Furthermore, our study showed for the first time that the mRNA levels of MYL6 increase in sepsis, consistent with ACSL4 results." (PMID 39262873, 2024). "The mRNA levels of MYL6 and ACSL4 in the LPS group were increased in vitro and in vivo experiments of sepsis-induced ALI models." (PMID 39262873, 2024). "To investigate the potential role of disulfidptosis in sepsis-induced ALI, first we used GEO2R online analysis software to identify DEGs and then intersected with DRGs to obtain the key genes: ACSL4 and MYL6." (PMID 39262873, 2024). "As SNPs affect gene expression and function, we can speculate that SNPs in the MYL6 gene may affect the progression of sepsis and the occurrence of ALI by affecting the expression of these genes in sepsis." (PMID 39262873, 2024). "We identified two key disulfidptosis-related DEGs in sepsis: ACSL4 and MYL6." (PMID 39262873, 2024). "Finally, we designed a validation study to investigate the differential expression of MYL6 and ACSL4 in sepsis-induced acute lung injury." (PMID 39262873, 2024). "Both in vivo and in vitro results were consistent, indicating higher ACSL4 and MYL6 mRNA levels in LPS-induced septic mice and cells, suggesting that ACSL4 and MYL6 may be potential therapeutic targets for sepsis-induced ALI." (PMID 39262873, 2024). "In addition, both in vivo and in vitro results have shown that in LPS-induced septic mice and cells, much higher ACSL4 and MYL6 mRNA levels were displayed, suggesting ACSL4 and MYL6 may possess the capacity to influence sepsis by inflammation response and immune infiltration." (PMID 39262873, 2024).
vasculitis (1 paper, 2022). "The Birmingham vasculitis activity score (BVAS) of anti-MYL6 antibody-positive MPA patients was significantly lower than anti-MYL6 antibody-negative MPA patients." (PMID 36527167, 2022).
tumor (16 papers, 2013 to 2025). "MYL6, a gene that encodes hexameric ATPase cellular motor protein, is upregulated in circulating tumor cells of many cancers." (PMID 35910195, 2022). "MYL6 has a poor prognosis with high expression in eight tumor types (GBMLGG, LGG, ACC, UVM, LAML, MESO, STES, STAD) and a poor prognosis with low expression in four tumor types (SARC, KIRC, THYM, OV)." (PMID 39329952, 2024). "In the spatial view of the ψ distribution for MYL6 exon 6, we found that regions enriched for tumor cells show very high inclusion of this exon, while regions enriched for myeloid cells show low inclusion rates." (PMID 36993612, 2023). "The two isoforms of MYL6 are enriched in different cell groups, with dominance of MYL6–218 in tumor epithelial cells and dominance of MYL6–207 in macrophages and CD8 cells." (PMID 36993612, 2023). "MYL6 was commonly expressed in all the seven major types of cells, which had a significantly higher expression level in fibroblasts, endothelial cells, and B cells/plasma cells in tumor compared with normal tissue." (PMID 38694875, 2024). "With the exception of FLNB and MYL6, the remaining 13 DRGs were significantly differentially expressed in the normal and tumor groups of the pancreas, and most DRGs shows higher expression in tumor groups." (PMID 38097783, 2023). "Specifically, an elevation in the expression levels of PRN1, OXSM, SLC3A2, and CD2AP were observed in tumor tissues, while the expression levels of DSTN, FLNA, TLN1, IQGAP1, MYL6, NCKAP1, and NDUFS1 declined in tumor tissues." (PMID 39995998, 2025). "Results showed that ACTB, DSTN, FLNA, IQGAP1, MYL6, and TLN1 were overexpressed in normal tissues, while CD2AP and INF2 were overexpressed in tumor tissues." (PMID 37325625, 2023). "Then, silencing lnc-MAFG-AS1 expression is found to impede the tumor progression of HCC both in vitro and in vivo by interacting with NM IIA subunits (MYH9, MYL12B, and MYL6)." (PMID 36034393, 2022). "Seven proteins (MYL6, AKAP9, ALDR, HS71A, KHDR1, ROA3, TAGL2) were part of both the BMI1 and RYBP chromatome, four of which (AKAP9, MYL6, ALDR and TAGL2) were identified as upregulated in IDH-wild type GBM samples versus non-tumour using TCGA datasets." (PMID 34316702, 2021). "Four spots were found with low expression in the central part of the tumor compared to the non-involved part, including MYL6 (spot 0210), spot 2305, spot 4807 and FABP1 (spot 5105)." (PMID 34563043, 2021).
cancer (12 papers, 2013 to 2024). A tumor composed of atypical neoplastic, often pleomorphic cells that invade other tissues. "The hypermethylated genes SLC7A11 and CD2AP were primarily associated with better prognosis in cancer, whereas the hypomethylated gene MYL6 was predominantly associated with poor prognosis in PCPG." (PMID 38862242, 2024). "The identification of ACTB, ACTN4, INF2, and MYL6 as DEDRGs that are implicated in both PD and various cancer types opens up exciting possibilities for developing novel therapeutic strategies for human patients." (PMID 39329952, 2024). "Aberrant expression of ACTB and MYL6 is associated with invasion and metastasis in many cancers." (PMID 38116315, 2023). "Based on many present studies, the influence of ACSL4 and MYL6 on cell structure and movement is closely related to the occurrence and development of cancer, inflammation, ischemia–reperfusion, and other diseases." (PMID 39262873, 2024). "In conclusion, our study highlights the potential of ACTB, ACTN4, INF2, and MYL6 as therapeutic targets and biomarkers for PD and cancer." (PMID 39329952, 2024). "The M1 stage was more prevalent in ACC patients with SLC7A11high, and MYL6 played an important role in cancer cell migration." (PMID 37919768, 2023). "This study found that ACTB, ACTN4, INF2, and MYL6 are closely related to PD and pan-cancer and can be used as candidate genes for the diagnosis, prognosis, and therapeutic biomarkers of neurodegenerative diseases and cancers." (PMID 39329952, 2024). "So far, it remains unclear how a reduction in MYL6 enhances cancer cell migration." (PMID 35205819, 2022). "In pan-cancer, the high expression of ACTB, ACTN4, and MYL6 in GBMLGG, LGG, MESO, and LAML had a poor prognosis, and the high expression of INF2 in LIHC, LUAD, UVM, HNSC, GBM, LAML, and KIPAN had a poor prognosis." (PMID 39329952, 2024). "Most cancer types showed a negative correlation between disulfidptosis-related genes and methylation, expected for TLN1 and MYL6." (PMID 38584831, 2024).
infection (1 paper, 2024). The state of being infected such as from the introduction of a foreign agent such as serum, vaccine, antigenic substance or organism. "The expression of the MYL6 gene in lung tissue affects the regulation of inflammatory response or the ability of lung tissue to cope with infection." (PMID 39262873, 2024).
MYL6 also shares sentences with these, for which no sentence is quoted: asthma (3 papers); breast carcinoma (2); cervical cancer (2); COVID-19 (1); glioma (1); heart failure (1); lung (1); lung injury (1); lung squamous cell carcinoma (1); neuroblastoma (1); neurodegenerative disease (1); prostate adenocarcinoma (1); rhabdomyosarcoma (1).